Y_RNA (Y RNA )
Gene: Miscellaneous RNA gene on chromosome 3 (57,493,667 to 57,493,780, forward strand). Ensembl gene ENSG00000212392.
Homologues: Orthologues: chimpanzee Y_RNA (99% identical), macaque Y_RNA (97% identical). Paralogues in human: Y_RNA (84% identical), RNY1P5 (82% identical), Y_RNA (82% identical), Y_RNA (81% identical), Y_RNA (80% identical), Y_RNA (79% identical), Y_RNA (78% identical), Y_RNA (77% identical), Y_RNA (76% identical), Y_RNA (75% identical), RNY1P1 (75% identical), RNY1P6 (74% identical), and 96 more.